IFNG (interferon gamma)
Diseases named in the same sentence as IFNG in open-access papers (continued):
Sharing a sentence is not in itself a finding about the gene and the disease.
tumor (continued). "Some level of tumor microenvironment characterization can often be achieved by genome and transcriptome-based technologies (including granzyme b/IFNg), flow cytometry and simple tumor cell killing assays but these are not cell specific." (PMID 33922052, 2021). "In vitro analysis highlighted an immunosuppressive cytokine profile in tumour involved lymph nodes consisting of higher levels of IL6, IL10, and TNFα released under stimulation, while IFNγ release was high in cells from tumour free lymph nodes." (PMID 34640541, 2021). "Loss of PTEN, a tumor suppressor and a member of PI3K-AKT pathway, upregulates the expression of immunosuppressive cytokines and downregulates the expression of IFNG to inhibit T-cell mediated infiltration." (PMID 34970257, 2021). "We have shown that inhibition of CXCR4 releases the matrix‐retained, now active CD8 TIL (as Ifnγ and Gzmb expression was elevated) to infiltrate the tumor tissue thus increasing tumor cell death and reducing tumor growth and subsequently metastasis." (PMID 33988305, 2021). "While PD-1 is expressed almost exclusively by lymphocytes, PD-L1 expression can be triggered by TIL-secreted IFNγ in multiple cell subtypes of the tumor microenvironment, including the cancer cells." (PMID 33498251, 2021). "RAE-1γMCMV primed OT-1 cells produced lower amounts of IFNγ, TNFα and IL-2, showed decreased degranulation potential, while simultaneously exhibiting similar cytotoxicity against tumor cells expressing their cognate antigen." (PMID 34168650, 2021). "Activated NK cells and T cells secrete IFNγ, and exposure to IFNγ leads to PD‐L1 overexpression in cancer cells, resulting in tumor escape from host immunity." (PMID 33491334, 2021). "We therefore conclude that tumour-specific, IFNγ-producing T cells were significantly increased in mice treated with radiation and checkpoint blockade, consistent with augmentation of T cell priming and activation." (PMID 34784792, 2021). "For example, IL1β is required by CD56bright NK cells to produce IFNγ to activate pyroptosis, necessary for the anti-microbial and anti-tumor activity of NK cells." (PMID 34447383, 2021). "IFNG release by CAR T cells sensitizes tumor cells to antigen-independent cytotoxicity by upregulating expression of death receptors such as the FAS receptor." (PMID 34771652, 2021). "When co-cultured with either 90Y-NM600-treated MOC2 or 90Y-NM600-treated B16 cells, CD8+ T cells exhibited increased expression of IFNγ, as compared to those co-cultured with untreated control tumor cells." (PMID 33995649, 2021). "PD-L1 surface expression was shown to be elevated on tumour cells following radiotherapy, which has been attributed to IFNg release from tumour-infiltrating lymphocytes (TILs)." (PMID 34733287, 2021). "Consistent with this, TCRβ sequencing demonstrated that OT-1 was the most abundant T-cell clone in both blood and tumors, and treatment with mRBC-OVA-4-1BBL-IL-12 increased the percentage of polyfunctional (granzyme B+IFNγ+) tumor-infiltrating OT-1 cells." (PMID 33976146, 2021). "Solid tumor eradication requires simultaneous destruction of the tumor stroma by T cell effector molecules such as IFNG." (PMID 33801448, 2021). "In five of 13 evaluable patients, enhanced antigen-specific CD4+ and CD8+ T-cell responses in ex vivo expanded PBMC were detected by intracellular IFNγ staining upon re-stimulation with tumor mRNA-transfected PBMC." (PMID 33858437, 2021). "Remarkably, the tumor inhibition rate of the SFV/IFNg+Pam3 treatment group was higher than that of the SFV/IFNg alone group (59.6% and 49.1%, respectively, versus the corresponding PBS groups)." (PMID 34835178, 2021). "Cyclophosphamide significantly enhanced IFNγ+ tumor-specific T-cell responses and markedly delayed tumor growth in mCRC patients." (PMID 34178645, 2021).
tumor (continued). "We also found that cytokines, including interferon-gamma (IFNγ) and tumor necrosis factor-alpha (TNFα) secreted by activated T cells, damaged tumor cells in a cell contact-independent manner." (PMID 32666260, 2021). "Of interest, CD4 positive and CD8 positive T cells of CD200high NB were shown to produce less interferon gamma and tumor necrosis factor alpha thereby inhibiting anti-tumor immunity." (PMID 34026614, 2021). "For example, cetuximab-activated NK cells were found to express PD-1 and to induce the expression of PD-L1 on tumor cells upon IFNγ release." (PMID 33572396, 2021). "IFNγ is often secreted by activated T cells and regulates immune responses and tumor immunosurveillance." (PMID 34496886, 2021). "It was shown previously that tumor-infiltrating T cells gradually lose their capacity to produce IFNg through post-transcriptional inhibitory events, meaning they fail to clear malignant cells." (PMID 34835178, 2021). "In particular, CD8+ tumor-infiltrating lymphocytes (TILs), T helper 1 (TH1) CD4+T cells and macrophages migrate into the tumor microenvironment, and elicit IFNγ secretion and anti-tumor effect." (PMID 34671202, 2021). "Activation of iNKT cells by α-GalCer leads to robust IFNγ release followed by increased expression of PD-1, resulting in anergy and inhibition of anti-tumor function." (PMID 34680322, 2021). "In concordance, the inflamed tumor surrogate biomarker, programmed death ligand 1 (PD-L1) is used as a single analyte or the interferon gamma (IFN-γ) tumor immune signature as a multi-analyte, to represent T cell inflamed or non-inflamed tumors." (PMID 33776991, 2021). "Those were IFNγ responsive in vitro, a quality that is required of tumor cells for recognition and elimination by CD8 T cells." (PMID 34232958, 2021). "Tumor RNA sequencing analysis confirmed pathways of inflammation and CD4 and CD8 T-cell activation to be common between the PD-1 ab-treated and PD-1cKO mice and a dominant IFNγ response in the tumor microenvironment." (PMID 34912335, 2021). "In several clinical trials of head and neck cancer, combination treatment of ex vivo activated iNKT cells and α-GalCer-loaded-DCs led to increased circulating iNKT cells and IFNγ production, leading to stable disease or tumor regression in patients." (PMID 34680322, 2021). "In mouse tumor models, a single intratumoral injection promoted tumor regression, which required IFNγ and CD8+ T cells." (PMID 33858437, 2021). "The tumor inhibition rate of the SFV/IFNg+Pam3 treatment group versus the PBS group was 59.6%, whereas SFV/Luc+Pam3 treatment reached only 27.8% versus the PBS group, indicating the therapeutic activity of IFNg." (PMID 34835178, 2021). "We demonstrated that IR elicited A549 cell apoptosis and augmented PBMCs-mediated tumor cell death through prohibiting IFNγ-mediated phosphorylation of STAT1 and STAT3 and gene expression of PD-L1 and MCL1." (PMID 34685495, 2021). "EZH2 inhibitors or CRISPR-mediated EZH2 depletion increased antigen presentation in the tumor cells, and increased antigen-specific CD8+ T-cell proliferation, IFNγ production and tumor cell cytotoxicity." (PMID 34680389, 2021). "Subtraction of baseline IFNγ spot counts revealed that both mRIPO and LPS treatment generated tumor antigen-specific (SIINFEKL) IFNγ+ T cells." (PMID 33767151, 2021). "Multiplexed gene activation of Cd70, Cd80, Cd86, Ifnα4, Ifnβ1, and Ifnγ was achieved in mice using a CRISPRa gRNA library improving immunogenicity of the transduced cells and leading to tumor rejection in vivo." (PMID 34163486, 2021). "Through the secretion of factors such as interleukin 6 (IL-6) or interferon gamma (IFNγ), which are responsible for immune cell mobilization, they can indirectly suppress tumor progression." (PMID 33430277, 2021). "To link the inhibition of LLC1 tumor growth by D-Nap-GFFY-T317 to activation of IFNγ expression, we initially determined changes of serum IFNγ levels." (PMID 33456564, 2021).
tumor (continued). "IFNγ levels were the lowest in cluster 3 despite the presence of active caspase-1 in tumor cells and high IL-18 levels." (PMID 33430344, 2021). "Murine colon carcinoma tumor models showed that low-dose radiotherapy-mediated tumor PD-L1 expression is induced by CD8+ T cell IFNγ signaling and peaks at 72 hours after treatment." (PMID 34025657, 2021). "The efficacy of PD-1 immune therapy has also been shown to depend on interferon gamma (IFNγ) sensing by tumor cells in the tumor microenvironment, which can be regulated by tyrosine-protein phosphatase non-receptor type 2 (Ptpn2)." (PMID 34912335, 2021). "Cytotoxic T lymphocyte cells (CTLs, CD3+ CD8+ IFNγ+) played the major antitumor effect in tumor milieu." (PMID 33462141, 2021). "By examining the functional properties of T cells in the tumor-draining LNs in mice that had received treatments for 5 weeks, we detected higher numbers of IFNγ and TNFα-producing CD4+ and CD8+ T cells after in vitro restimulation." (PMID 33408092, 2021). "A comparison of the repertoires of IFNγ-positive and -negative cells shows a prominent enrichment of certain clones with putative tumor specificity among the IFNγ+ fraction." (PMID 34576023, 2021). "The activated IFNγ has potent cytotoxic effect to tumor cells and inhibits angiogenesis in tumors, thereby reducing growth of xenografted or carcinogen-injected tumors without adverse effects on the liver and lipid metabolism." (PMID 33456564, 2021). "TNFα promotes the cytolysis of tumor cells while IFNγ upregulates immunosuppressive molecules to dampen the anti-tumor immune response." (PMID 34869307, 2021). "Interferon-gamma (IFN-γ) is a main cytokine that is produced and secreted by several types of immune cells including T lymphocytes and natural killer cells present in the tumor microenvironment." (PMID 34500779, 2021). "Mechanistically, SHP099/TNO155 induced these effects through targeting SHP2 in cancer cells and augmenting cancer cell IFNγ signaling in the context of tumor-immune cell crosstalk." (PMID 33446805, 2021). "Whereas CD8+ T cells and IFNγ-producing Thelper (Th) 1 cells exhibit potent anti-tumor functions and are generally of good prognosis in solid tumors, their Foxp3+ regulatory T cell (Treg cells) counterparts are master inhibitors of cancer immunity." (PMID 33572260, 2021). "The more production of IFNγ by D-Nap-GFFY-T317 injection than T317 oral administration resulted in further inhibition of tumor growth." (PMID 33456564, 2021). "In detail, low expression of major histocompatibility complex (MHC) antigen leads tumor cells to evade the host immune response against tumor cells, and treatment with IFNγ activates the MHC antigens, resulting in tumor regression." (PMID 34572592, 2021). "Inactivation of IFNγ signaling in tumor cells represents a major challenge to this approach and confers resistance to ICB." (PMID 34201655, 2021). "Tumor-infiltrating monocytes and macrophages suppress the function of NK cells by repress interferons-γ (IFNγ), TNFα, and Ki-67 expression of NK cells through TGFβ1." (PMID 33406733, 2021). "Radiotherapy alone can elicit antitumor T-cells that infiltrate the tumor and produce interferon-gamma (IFN-γ), which, in turn, induces PD-L1 expression on tumor cells." (PMID 34830880, 2021). "In CRC context, some studies demonstrated that oncogenic KRAS is able to reduce the expression of IFNγ targeted genes in KRASMUT tumor cells (HCT-116 cells with KRASG13D), including STAT1 and MHC-II." (PMID 33691728, 2021). "The rationale for exploring the TNF/IL12 combination, in addition to TNF alone, relies on the notion that IL12 can induce IFNγ in the tumor microenvironment, a cytokine known to be critical for the activity of vasculature-targeted TNF." (PMID 33952242, 2021). "In summary, we concluded that tumor treatment with SFV/IFNg led to an increase in Th and CTL cells and a decrease in T-regs in the CD4+ cell population." (PMID 34835178, 2021).
tumor (continued). "Blockage of PD-L1 can restore IFNγ/TNF-α production in BTLAPD-1 tumor CD4+T cells, but partially inhibit the activation of BTLAPD-1 CD4+T cells." (PMID 34869376, 2021). "Of the five GSDM gene members, only GSDMD expression showed a positive correlation with CD8+ T cell marker genes (e.g., CD8A, CD8B, PRF1, GZMA, GZMB, and IFNG) in CTLs across all three tumor cohorts." (PMID 34429144, 2021). "In this study, we demonstrated the importance of IFNγ signaling in our tumor model by knocking out the IFNγ receptor, IFNGR1; we observed impaired T cell-mediated tumor killing as well as attenuated MHC class I expression in co-culture." (PMID 33446805, 2021). "The killing ability of Vγ2Vδ2 T cells induced by Y111 prompted us to check the production of killing cytokines, including IFNγ and TNFα, and cytotoxic mediator granzyme B in the co-culture of the T cell and tumor cells." (PMID 34040604, 2021). "M1-like macrophages are “classically activated” (via LPS, IFNγ, or GM-CSF) and have a pro-inflammatory and anti-tumor phenotype." (PMID 34829860, 2021). "These ICDs, together with RT-induced senescence-associated secretory phenotype (SASP), activate T cells and recruit them into tumor sites, whereas interferon gamma (IFNγ) secreted from CD8+ T cells further promotes RT-induced ferroptosis." (PMID 33891303, 2021). "L1CAM-specific CAR T cells were more strongly activated in the bioprinted 3D tumor model, but induced less IFNG release than in 2D cocultures." (PMID 34267756, 2021). "In vivo, SHP2 inhibition also increased tumor IFNγ signaling and displayed anti-tumor activity by promoting cytotoxic T cell function and inhibiting immune suppressive myeloid cells." (PMID 33446805, 2021). "Although there are contradictory results in different papers, these downregulations at mRNA level would help tumor cells to defeat the anti-cancer properties of interferon gamma signaling." (PMID 34249670, 2021). "Chronic exposure to IFNγ enhanced tumor growth in a mouse xenograft model with hepatoma and mammary adenocarcinoma cells." (PMID 33578830, 2021). "Together, these data indicate that patients bearing IFNγ signatures, yet still have a growing tumor, have mounted an immune response against their tumor that was subsequently repressed." (PMID 33816320, 2021). "One potent inducer of PD-L1 expression is interferon-gamma (IFN-γ), a critical cytokine in functional anti-tumor immune responses." (PMID 34064795, 2021). "IFNγ produced by activated cells of the innate and adaptive immunity induces the expression of PD-L1 on the surface of tumor cells and myeloid cells such as macrophages and myeloid-derived suppressor cells." (PMID 33498238, 2021). "On the other hand, IFNγ also induces PD-L1 expression on tumor cells, T cells, myofibroblasts and macrophages, thereby supporting CTL inhibition and immune escape in PDAC." (PMID 34638420, 2021). "Taken together, pathologic complete responses, IFNγ and exhausted T cell populations, and decreases in tumor size via imaging studies are strong forerunners to serve as robust biomarkers of neoadjuvant ICB response." (PMID 35087529, 2021). "This indicates that IFNγ is a vital mediator of tumor immune evasion and a potential target for improving clinical responses to immunotherapy." (PMID 34312372, 2021). "Increased in vivo efficacy by A2AR-knockdown CAR T cells was associated with increased expression of effector-related genes in tumor-infiltrating CD8+NGFR+ CAR T cells such as IFNγ, TNF, IRF4, and Granzyme B." (PMID 34050151, 2021). "NK cells have been found to be dysfunctional within the tumour microenvironment (TME) of HCC with a marked reduction in interferon-gamma (IFN-γ) and TNF-α production in both the intra-tumoral and peripheral NK cell populations compared to healthy individuals." (PMID 34888493, 2021). "At the tumor site, pro-tumor TANs reduce T cell proliferation and IFNγ production and induce T cell apoptosis to suppress T cell-mediated immunity." (PMID 33670082, 2021).
tumor (continued). "The PD-1 ligand is expressed on both tumor cells and cells in the tumor microenvironment, and its action depends on inflammatory stimuli, such as interferon-gamma." (PMID 34976532, 2021). "Gal-9 is likely upregulated early on during cross-presentation of tumor antigens when intratumoral DCs sense danger signals from dying tumor cells, but is only secreted in large quantities after T cells are activated to produce IFNγ." (PMID 33547304, 2021). "In situ, the combined detection of TNFRSF9, TNF, and IFNG identified most of the tumor-specific reactive TIL repertoire." (PMID 34707600, 2021). "In contrast, lack of IFNγ expression enhanced expression of VEGFR and CD31 in tumors, indicating the importance of IFNγ expression in suppressing tumor angiogenesis." (PMID 33456564, 2021). "TGF-β/IL-10 genes, known to play critical roles in inhibiting CD8 and CD4 T cell functions and IL-2/IFNγ genes, which are known to boost the anti-tumor immune response." (PMID 34728682, 2021). "Both IFNIs and IFNγ increase macrophage activity by polarizing immature monocytes into a mature anti-tumor M1 phenotype." (PMID 33801234, 2021). "In lung cancer, IL-18 contributes to the expansion of CD8+ Tbet+ TILs that express IL-18 receptors and produce IFNγ within the tumor microenvironment." (PMID 33430344, 2021). "In the periphery, combination therapy elicited a significant EMT6 tumor-specific IFNγ response (day 21), sustained 6 days after treatment cessation (day 25); both correlated with tumor size reduction." (PMID 34446712, 2021). "CD8 T lymphocytes are able to exert their anti-tumour cytotoxic effects via the secretion of TNFα and IFNγ leading to the apoptosis of tumour cells, when the T-cell receptor (TCR) binds its cognate peptide:MHC antigen expressed on tumour cells." (PMID 33995362, 2021). "For instance, using a mouse model of sarcoma, Chang and colleagues found that the high energy requirements of tumour cells trigger a competition for glucose that results in blocking of glycolysis in IFNγ-producing effector T cells and tumour progression." (PMID 34932167, 2021). "As IFNγ is required for tumor immune surveillance, we assessed the relative importance of IFNγ-driven antitumor immunity in conferring increased phenformin sensitivity." (PMID 34083537, 2021). "The percentage of CD3+ T cells, the proportion of CD4+, CD8+ and Treg subsets and the level of IFNγ production was heterogeneous between tumor samples." (PMID 34290245, 2021). "Over time, tumor infiltrating T cells become less responsive to antigens, release less IFNγ, and kill fewer malignant cells." (PMID 33801234, 2021). "UniCAR 28/ζ-armed NK-92 cells as well as UniCAR stop and Vector control cells secreted comparable basic levels of IFNγ in the presence of tumour cells." (PMID 32034289, 2020). "Clinical studies that specifically direct cytokines such as TNF or IFNγ to the tumor endothelium via peptides or single‐chain antibodies are already underway." (PMID 31916677, 2020). "Similar frequencies of CD3+, CD4+, and CD8+ T cells were found in draining lymph nodes from RANK+/+ and RANK−/− tumor transplants, but a moderate increase in IFNγ production in the lymph node T cells was observed in the RANK−/− tumor transplants." (PMID 33303745, 2020). "The current assays such as Enzyme-Linked Immunosorbent Spot (ELISpot) for the detection of cytokine and IFNγ secreting cells show limited sensitivity in assessing tumor-specific T-cell responses." (PMID 32258038, 2020). "First, iNKT cells can produce an abundant amount of Th-1 type cytokines such as IFNγ and TNFα, which can promote an inflamed immune-microenvironment beneficial for anti-microbial or anti-tumor immunity." (PMID 33329531, 2020).